EGFR (epidermal growth factor receptor)
Diseases named in the same sentence as EGFR in open-access papers (continued):
Sharing a sentence is not in itself a finding about the gene and the disease.
lung adenocarcinoma (continued). "Another study has shown that resistin activates Toll-like receptor 4 (TLR4) and engages with the Src pathway which activated the EGFR phosphorylation and increased epithelial-mesenchymal transition (EMT), subsequently inducing the migration and invasion of lung adenocarcinoma." (PMID 33313320, 2020). "The clinical value of combined local radiation and epidermal growth factor receptor (EGFR)-tyrosine kinase inhibitors (TKIs) for medically inoperable and TKI-naïve early-stage lung adenocarcinoma patients with EGFR mutations has not yet been determined." (PMID 32660443, 2020). "In this study, we used FFPE tissue specimens collected from lung adenocarcinoma patients who did not receive any EGFR tyrosine kinase inhibitors, such as osimertinib." (PMID 32983988, 2020). "Furthermore, KLF6 downregulation was correlated with activated EGFR and phosphorylated AKT in patient-derived lung adenocarcinoma samples and decreased KLF6-induced resistance to erlotinib both in vitro and in vivo." (PMID 32552913, 2020). "Studies in the past decade have reported that tyrosine kinase inhibitors (TKIs) targeting epidermal growth factor receptor (EGFR), anaplastic lymphoma kinase (ALK), and ROS proto-oncogene 1 (ROS1) are potential therapeutic targets for lung adenocarcinoma, upon genotyping." (PMID 33072571, 2020). "The two EGFR‐positive advanced lung adenocarcinoma never smoker female patients (58 years old, T4N2M1, L858R; 61 years old, T2N3M1, 19Del) were administered gefitinib and subsequent osimertinib." (PMID 32239624, 2020). "In the same line, after dcEF stimulation (dcEF: 0–450 mV/mm, 0–8 h), lung adenocarcinoma H1975 cells move toward the cathode, and EGFR is related to cell migration without electric field stimulation rather than cell movement with electric field stimulation." (PMID 32210363, 2020). "To assess the role of MSCs in NSCLC metastasis, we employed a panel of EGFR-mutant human lung adenocarcinoma cells primed by pre-incubation with or without bone marrow-derived MSCs." (PMID 33119681, 2020). "Comparison of baseline characteristics between TKI-responders and non-responders in EGFR positive lung adenocarcinoma." (PMID 32053675, 2020). "The Iressa Pan-Asia Study (IPASS) trial was the first randomized clinical trial to compare EGFR-TKI with chemotherapy in patients affected by lung adenocarcinoma who were former light smokers or nonsmokers." (PMID 32397295, 2020). "Second, different PD-L1 expression levels did not affect the efficacy of first-line EGFR-TKIs in treating stage IV EGFR mutant lung adenocarcinoma patients, neither in response nor TTF." (PMID 32092879, 2020). "The reason is that currently FDA-approved targeted drug therapies, such as epidermal growth factor receptor (EGFR) mutation or EML4-ALK fusion-based targeted therapies, are mainly suitable for lung adenocarcinoma (LUAD) but not for LSCC patients." (PMID 32140187, 2020). "More recent work showed that unlike wild type (WT) EGFR, mutant EGFR phosphorylates Mig-6 and phosphorylated Mig-6 negatively regulates the degradation of EGFR mutants in lung adenocarcinoma." (PMID 32552717, 2020). "In the past decade, studies have identified tyrosine kinase inhibitors (TKIs) targeting epidermal growth factor receptor (EGFR), anaplastic lymphoma kinase (ALK), and ROS proto-oncogene 1 (ROS1) as potential therapies for lung adenocarcinoma on the basis of genotyping." (PMID 32607285, 2020). "The EGFR KDD has been described previously in rare cases of glioblastoma and lung adenocarcinoma." (PMID 32490123, 2020). "EGFR insertions and deletions are found in roughly 15% of lung adenocarcinomas in the US, with increased frequency in nonsmokers (43% vs. 11% in smokers) and Asians (up to 60% in Asian women)." (PMID 30741509, 2019).
lung adenocarcinoma (continued). "Curcumin also exhibited its proapoptotic activity in lung adenocarcinoma cells by suppressing expression of COX-2, EGFR, and extracellular signal-regulated kinase (ERK) 1/2 activities, which correlated with elevated apoptosis and reduced survival of lung adenocarcinoma cells." (PMID 31590362, 2019). "In adenocarcinoma, PD-L1 expression using 22C3 assay at clinically relevant cutoff could be predicted in higher N stage, histologically solid pattern, wild-type EGFR, and ALK positive in lung adenocarcinoma." (PMID 31561631, 2019). "Advanced lung adenocarcinoma is characterized not VGFR2-hyperactivated but altered EGFR signaling pathway." (PMID 31570733, 2019). "For instance, EGFR and KRAS genes are frequently mutated in lung adenocarcinomas but with no overlap in individual samples." (PMID 30422399, 2019). "One patient did not detected EGFR or ALK mutation in the metastatic tumor, but the primary lung adenocarcinoma did harbor an EGFR mutation." (PMID 31455365, 2019). "In the entire cohort, 336 (80.8%) patients were histologically diagnosed as lung adenocarcinoma (ADC), 269 (64.7%) were non-smokers, 169 (40.6%) harbored EGFR mutations, and 167 (40.1%) were EGFR-FISH (+)." (PMID 30823937, 2019). "The patient did not harbor any activating mutation of EGFR, KRAS, or ALK genes; he was diagnosed as poorly differentiated lung adenocarcinoma stage 2B at the age of 51 and was a light smoker that used one pack per year." (PMID 31083279, 2019). "In the present study, we describe the molecular epidemiology of EGFR, KRAS, BRAF, ALK and MET genetic alterations and their correlations with the demographic and clinical characteristics of 1440 Sardinian patients with lung adenocarcinoma." (PMID 31711449, 2019). "ROS1 rearrangement with an incidence of 4% of lung adenocarcinoma which is EGFR and ALK negative represents an important targetable driver mutation in the Indian population." (PMID 30915158, 2019). "In lung adenocarcinoma (ADC) patients with FH_Any, EGFR was more likely mutated than those without (OR = 1.47[1.14–1.89], P = 0.003)." (PMID 31703574, 2019). "However, in lung adenocarcinoma (LUAD), c-Myc expression was correlated with HIF-1α and Glut1, and the expression of HIF-1α, EGFR, and Glut1 was related to each other in LUAD." (PMID 30967777, 2019). "In the never-smoking lung adenocarcinoma study, the DCBLD1 susceptibility locus was associated with EGFR mutations in exons 19 and 21 (in the tyrosine kinase encoding region)." (PMID 31878157, 2019). "Lung adenocarcinoma cell lines from different backgrounds were characterized based on protein expression levels measured for HSP90, other related HSPs and HSP90 client proteins such as EGFR and EML4-ALK." (PMID 31370342, 2019). "Patients with wild type of EGFR and ALK-positive lung adenocarcinoma may represent a potential selective group, which has a better chance of good response to immunotherapy." (PMID 31561631, 2019). "In conclusion, PD-L1 expression using a 22C3 assay at clinically relevant cutoff could be predicted in higher N stage, histological solid pattern, wild-type EGFR, and ALK positive in lung adenocarcinoma." (PMID 31561631, 2019). "ROS1 rearrangement with an incidence of 4% of lung adenocarcinoma which are EGFR and ALK negative represents an important targetable driver mutation in the Indian population." (PMID 30915158, 2019). "One limitation of our model is that it was built in early stage lung adenocarcinoma, for which treatment is surgery and external beam radiation therapy rather than EGFR inhibitor." (PMID 30559455, 2018). "Lung adenocarcinoma with EGFR-TKI resistance was reported to have higher abilities of invasion and migration than cancers sensitive to EGFR-TKI, but the function of matrix metalloproteinases (MMPs) has not been explored in EGFR-TKI–resistant lung adenocarcinoma." (PMID 29463039, 2018).
lung adenocarcinoma (continued). "Of interest, no BRAF mutations were found in lung adenocarcinomas that coexisted with BRAF-mutated AAH lesions, whereas four of five cases of BRAF-mutated AAH tumors coexisted with EGFR-mutated adenocarcinomas." (PMID 29690599, 2018). "In lung adenocarcinomas, we recapitulate the mutual exclusivity between KRAS and EGFR as well as the importance of TP5328, for which our model suggests that it is frequently co-mutated with both KRAS and others like MLL3, as well as KRAS and STK11 are frequently co-mutated." (PMID 30341300, 2018). "Our results above suggested that using EGFR tyrosine kinase inhibitors in primary PEAC patients might be unreasonable and inefficient, which was different from that in usual lung adenocarcinoma." (PMID 29587865, 2018). "The majority of patients with advanced lung adenocarcinomas harboring EGFR exon 20 insertions do not respond to treatment with EGFR-TKIs." (PMID 30445769, 2018). "The mRNA levels of the MMP-1 gene in two EGFR-TKI–resistant lung adenocarcinoma cells (PC9/GR and PC9/ER) were significantly higher than those in EGFR-TKI–sensitive cells (PC9/6m) (PC9/GR vs. PC9/6m, p = 0.0349; PC9/ER vs. PC9/6m, p < 0.0001; PC9/ER vs. PC9/GR, p < 0.0001)." (PMID 29463039, 2018). "Unfortunately, EGFR mutations and ALK fusions are typically not present in LUSC28, and novel targeted agents for adenocarcinoma of the lung ineffective against LUSC." (PMID 30367091, 2018). "Recently, human lung adenocarcinoma cells (A549 cell line), when exogenously treated with SP-D, showed suppressed epidermal growth factor (EGF) signaling by reducing the EGF binding to EGFR, which subsequently reduced the cell proliferation, invasion, and migration of cancer cells." (PMID 29915574, 2018). "Currently, there is no consensus about which drug to use in Asian patients with EGFR-mutant lung adenocarcinoma and brain metastases." (PMID 30458751, 2018). "Our study showed that in addition to smoking status, CSD is an important independent negative predictive factor of EGFR-TKI treatment outcome and efficacy in patients with lung adenocarcinoma with activating EGFR mutation." (PMID 30055587, 2018). "Furthermore, JAK2 inhibition can sensitize resistant EGFR-mutant lung adenocarcinoma to tyrosine kinase inhibitors, which suggests the potential utilities of JAK inhibitors toward the treatment of EGFR-TKI-resistant NSCLC." (PMID 30483119, 2018). "Rearrangement of the anaplastic lymphoma kinase (ALK) gene is an oncogenic driver event typically occurring in young non-smokers suffering from a KRAS/EGFR wild-type lung adenocarcinoma." (PMID 30326973, 2018). "Five patients previously underwent surgery for early-stage tumors, 4 patients were recurrent ones (progressive disease) from previous treatment of first generation of EGFR-TKIs, and the remaining 100 patients were newly diagnosed with treatment naïve at stages of IIIB to IV lung adenocarcinoma." (PMID 28829813, 2017). "To illustrate this point, we investigated the molecular basis of targeted therapy resistance in a 41-year old male never-smoker with advanced EGFR-mutant (L858R) lung adenocarcinoma." (PMID 28287179, 2017). "We observed no strong positive correlations for lung adenocarcinoma, providing evidence that the transcriptional effects of mutations in KRAS, EGFR, MET, NTRK1, and PIK3CA are distinct from each other." (PMID 29322935, 2017). "This is even more clinically relevant since recent studies demonstrated a significant therapeutic benefit of trastuzumab (an anti-ERBB2 mAb) and of newer TKIs, such as afatinib and neratinib, which target both EGFR and ERBB2, in selected patients with lung adenocarcinoma." (PMID 28881604, 2017). "Currently, there is no defined role of EGFR TKIs for patients with Stage I to III lung adenocarcinoma." (PMID 29312641, 2017).
lung adenocarcinoma (continued). "For example, MET amplification can be detected after the treatment of the first generation of EGFR-tyrosine kinase inhibitor (EGFR-TKI), gefitinib or erlotinib, in EGFR-mutant lung adenocarcinomas, and the combination of EGFR-TKI and MET inhibitor is demonstrated to be an effective treatment." (PMID 28158234, 2017). "The aim of this study was therefore to evaluate the occurrence of DVT/VTE in patients with EGFR- and ALK-mutated forms of lung adenocarcinoma compared with non-mutated cases." (PMID 28560038, 2017). "In this study, we selected 3 lung adenocarcinoma cell lines SPC-A1, SCH-1153 and A549, which were all inappropriate for TKIs due to the lack of EGFR mutations/ALK-fusions or possessing KRAS mutations." (PMID 29285248, 2017). "However, after an EGFR (MIM: 131550) exon 19 indel was identified by ONCOgenics, pathology review was performed and immunohistochemistry revealed that it was a primary lung adenocarcinoma." (PMID 28717660, 2017). "In lung adenocarcinoma, the presence of KRAS or the absence of targetable mutation are associated with PD-L1 expression, whereas EGFR or other common mutated adenocarcinoma rarely express PD-L1." (PMID 28671973, 2017). "The negative correlation between MIIP and EGFR protein expression was validated in lung adenocarcinoma samples." (PMID 26824318, 2016). "We performed amplification refractory mutation system (ARMS) fluorescence quantitative PCR to detect the gene status of EGFR, ALK, ROS1 and RET in resected samples from 280 patients who were confirmed to have primary lung adenocarcinomas with N1-N2 lymph node metastasis." (PMID 27563816, 2016). "In this study, we aimed to perform CGP on tumor specimens from patients with lung adenocarcinomas who tested negative for EGFR, KRAS and ALK previously at our institution." (PMID 26992220, 2016). "Studies have shown that most lung adenocarcinomas with wild-type EGFR were not highly sensitive to EGFR-TKIs." (PMID 26919104, 2016). "We show here that osimertinib suppresses glycolysis in parental EGFR-mutant lung adenocarcinoma lines, but has not in osimertinib-resistant cell lines." (PMID 27861144, 2016). "We presented the results of the EGFR, KRAS and ALK mutational analyses in patients with lung adenocarcinomas in a prospective study, regardless of clinical stage." (PMID 27655296, 2016). "EGFR, KRAS, and ALK alterations are the major genetic changes in lung adenocarcinoma." (PMID 26992209, 2016). "No other mutated pairs of genes demonstrated a similarly negative association in lung adenocarcinoma, further arguing that the mutual exclusivity of KRAS and EGFR mutations is due to negative selection." (PMID 26047463, 2015). "To screen for the expression of GAS5 in the NSCLC cell lines, we used qRT-PCR analysis to assess GAS5 expression in the A549 (K-RAS mutant, EGFR wild-type), H1299 (EGFR wild-type, N-RAS), H1975 (T790M EGFR mutant), and HCC827 (EGFR mutant) lung adenocarcinoma cell lines." (PMID 25925741, 2015). "The KIF5B-RET rearrangement is detected with the frequency of 1 ~ 2 % in ‘triple marker’-negative lung adenocarcinomas, i.e., EGFR, KRAS and EML4-ALK wild type." (PMID 26268359, 2015). "For example, miR-145 has been found to inhibit cancer cell growth, invasion, and metastasis by suppressing EGFR and NUDT1 in lung adenocarcinoma, FSCN-1 in esophageal squamous cell carcinoma, N-cadherin in gastric carcinoma, and IGF in hepatocellular carcinoma." (PMID 26514209, 2015). "In the Cohort 2 analysis, 29 of 295 patients with EGFR-wild type lung adenocarcinoma (9.8%) were found to have EML4-ALK translocation and none of them harbored other driver gene mutations." (PMID 25789627, 2015). "Therefore, it is of interest that lung adenocarcinomas, one of the subclasses of NSCLC, transform into SCLC in response to EGFR-TKI treatment." (PMID 26400668, 2015). "Unlike lung adenocarcinoma, pulmonary LELC rarely presents with EGFR mutations, KRAS mutations or ALK rearrangements." (PMID 26361045, 2015).
lung adenocarcinoma (continued). "HSP90 inhibition leads to the regression of EGFR L858R-driven murine lung adenocarcinoma, regardless of the presence of T790M." (PMID 25780909, 2015). "In lung adenocarcinomas, EGFR mutation was higher in female and non-smoking patients, KRAS mutation only in patients with wild-type EGFR gene was higher." (PMID 26582224, 2015). "EGFR/KRAS/ALK-negative lung adenocarcinoma in never-smokers is highly heterogeneous at the somatic mutation level." (PMID 24576404, 2014). "They include the prostate cancer suppressor NXK3-1, the gene CSMD1, which is recurrently deleted in melanoma, and the phosphatase DUSP4, which is involved in negative feedback control of EGFR signaling in lung adenocarcinoma." (PMID 25160065, 2014). "We screened 230 surgically resected lung adenocarcinoma samples to identify EGFR/KRAS/ALK-negative tumors in never-smokers." (PMID 24576404, 2014). "In lung adenocarcinomas, 2–4% present activating mutations within the kinase domain of ERBB2 analogous to those detected in EGFR and never coexisting with EGFR, KRAS, or ALK alterations." (PMID 25478327, 2014). "The frequency of EGFR, KRAS, HER2 mutations and EML4-ALK fusion were 75.3%, 2%, 5.9% and 5%, separately, in recent analysis of 202 lung adenocarcinoma samples from Chinese patients who never smoked." (PMID 24533074, 2014). "Alternatively, the EGFR variant III mutations have been found in lung SCC and gliomas, but not in lung adenocarcinoma." (PMID 24681604, 2014). "NTRK-1 fusions have been identified in 3 of 91 lung adenocarcinoma samples that were EGFR/KRAS/ALK-1/ROS-1 negative." (PMID 25505733, 2014). "The genomic makeup of EGFR/KRAS/ALK-negative lung adenocarcinomas in never-smokers is remarkably diverse." (PMID 24576404, 2014). "In conclusion, in the present study, the clinicopathological characteristics and the spectra of EGFR and KRAS mutations in lung adenocarcinoma were different between never and heavy smokers." (PMID 24179496, 2013). "In another study with 183 lung adenocarcinomas, MET amplification was observed in 8 (4%) patients with wild-typed EGFR and wild-typed KRAS, indicating that the presence of MET gene amplification might be mutually exclusive with EGFR and KRAS mutations." (PMID 27234388, 2013). "The clinicopathological characteristics and the spectra of the EGFR and KRAS mutations in lung adenocarcinoma were different between the never and heavy smokers." (PMID 24179496, 2013). "The purpose of the present study was to elucidate the differences in the clinicopathological characteristics of EGFR- and KRAS-mutated lung adenocarcinomas and their related mutation spectra between never smokers and heavy smokers." (PMID 24179496, 2013). "Taken together, EGFR and KRAS mutational status do not appear to be translated into a clearly distinctive and prominent expression signature in lung adenocarcinoma." (PMID 24205279, 2013). "The continued characterization of patient samples with integrated genomic, expression, and protein data will no doubt provide further insight into the regulation of EGFR-mutant lung adenocarcinoma." (PMID 24255704, 2013). "We also evaluated the expression of total and phosphorylated p70S6K in clinical EGFR TKI-sensitive and -resistant lung adenocarcinoma tumor tissues and found that p70S6K may be a good marker for selection of patients for whom ku-0063794 therapy is appropriate." (PMID 23874880, 2013). "Molecular pathway-specific therapies for lung adenocarcinoma, e.g., targeting mutant EGFR or ALK fusions, limit non-tumor toxicity and extend survival time compared to the conventional chemotherapies." (PMID 23976985, 2013). "The great success of targeted therapy with epidermal growth factor receptor (EGFR)-tyrosine kinase inhibitor (TKI): gefitinib and erlotinib, for treatment of lung adenocarcinoma has made targeted therapy become the most popular modality for major human cancers." (PMID 23951022, 2013).